CXCL12 (C-X-C motif chemokine ligand 12)
Diseases named in the same sentence as CXCL12 in open-access papers (continued):
Sharing a sentence is not in itself a finding about the gene and the disease.
infection (continued). "Amongst these, CXCL12 showed consistent, low-level expression starting immediately following infection at 1 dpi." (PMID 32119719, 2020). "In the presence of apical CXCL12 and after additional E-30 infection all T cell subpopulations displayed significant higher migration rates compared with the uninfected control conditions." (PMID 31752904, 2019). "Amongst cytokines, the genes for Cxcl9, Cxcl10, Cxcl13, Il-1β, Il-6, Tnf, Tnfsf10, IFN-γ, Ccl2, Ccl4, Ccl7, Ccl17, and Mif were highly up-regulated (ranging from 2- to 405-fold, p ≤ 0.05), whereas Cxcl12 and Cxcl14 were down-regulated during in vivo infection." (PMID 30857242, 2019). "infection, heightened levels of G-CSF led to a reduction in CXCL12 expression in the BM via Toll-like receptor and NOD1/2 signaling." (PMID 30619317, 2018). "It has been demonstrated that during IAV infection, the migration of neutrophils into the airways leaves behind a trail containing the chemokine CXCL12 that guides the recruitment of CD8+ T cells toward the site of infection." (PMID 29867955, 2018). "Infection led to a reduction of Cxcl12 mRNA accumulation in the bone marrow, correlating with a reduction in the number of CXCL12-expressing cells." (PMID 30619317, 2018). "Accordingly, the expression of the receptors for Ccl3 and Cxcl12, Ccr1 and Cxcr4, respectively, were significantly upregulated by the interaction of low diet and infection (p < 0.05)." (PMID 28397794, 2017). "The mRNA expression levels of the chemokines Ccl3 and Cxcl12 and the levels of Igf1 in thymocytes were clearly upregulated due to protein malnutrition or infection conditions separately (Ccl3 p < 0.01; Cxcl12 p < 0.05 and Igf1 p < 0.001)." (PMID 28397794, 2017). "It has been proved that gp120 causes impairment of the T cell response to CXCL12-induced chemotaxis, whereas CXCL12 inhibits infection by CXCR4-tropic virus." (PMID 29085362, 2017). "Supporting this interpretation, mice that lack neutrophil derived CXCL-12 display early defects in CD8+ T cell responses that recover by day 9 post-infection." (PMID 27741316, 2016). "The chemokine CXCL12 is important for B cell lymphopoiesis, but expression of this chemokine was only slightly reduced early after infection in Il1r1−/− mice." (PMID 27579026, 2016). "CXCL12 levels were decreased in the acute phase of infection for both rapid and classic progressors, and subsequently increased in the chronic phase." (PMID 27203285, 2016). "Detailed analyses of our data revealed that morphine induced an increase in CXCL12 generation in the presence of systemic infection." (PMID 26087960, 2015). "Obviously, CXCL12/SDF-1 was an excellent new target for the development of novel inhibitors of infection by T-tropic HIV-1 species." (PMID 26097474, 2015). "Its ligand CXCL12 is one of the three most important chemokines (CCL19, CCL21, and CXCL12) which directs DCs migrate from sites of infection to secondary lymphoid organs." (PMID 24734242, 2014). "We found no activation or even reduction in base-line expression for multiple molecules (IL-7, IL-4, IL-13, GATA3, ROR-γt, and CXCL12) at 2, 6 and 10 days post-infection." (PMID 25254971, 2014). "The CXCL12/CXCR4 axis thus appears to have a dual effect on the L. sigmodontis life cycle: by acting as a host-cell restriction factor for infection, and as a growth factor for worms." (PMID 22511975, 2012). "Infection with HCMV significantly decreased secretion of CXCL12 by SGHPL-4 cells, and induced a striking perinuclear accumulation of the chemokine." (PMID 23116176, 2012). "In accordance with this, we report here both a reduced CXCL12 production in the bone marrow and an influx of developing B cells in the spleen during the acute phase of infection." (PMID 21687602, 2011). "CXCL12 is also a potent chemokine involved in chemoattraction of T cells to the site of infection or inflammation." (PMID 21931802, 2011).
infection (continued). "In contrast, in X4LAI.04-infected tissues production of CCL3, CCL4, CCL5, CXCL10, and CXCL12 was significantly increased compared with that in uninfected tissues and reached a maximum 5 to 9 days post-infection." (PMID 20862220, 2010). "Immune response-associated genes, with altered expression in virulent strain infection, were selected for further investigation: Tlr2, Tlr4, Tlr13, Myd88, Il1b, Il6, dectin-2 and Cxcl12." (PMID 19845042, 2009). "The majority of these genes were upregulated, but a single cytokine gene, Cxcl12, was downregulated in the renal response to the virulent C. albicans strain and unchanged in attenuated strain infection." (PMID 19845042, 2009). "CXCL12 mRNA was significantly increased only in endothelial cells after infection, indicating that endothelial cells may be a source of plasma CXCL12 and not just serve as “sinks” for circulating CXCL12." (PMID 39773555, 2025). "Finally, expression of interleukins in general and CXCL12 specifically demonstrated infection and PM-specific patterns characterized by unique upregulation of IL24 following Winter PM and IL11 and CXCL12 upregulation following Spring PM co-exposure." (PMID 40671793, 2025). "We hypothesised that the increase in expression of Cxcl12/Ccl2/Ccr2 signalling axis components in miR-126 knockdown embryos is responsible for the recruitment of macrophages to infection." (PMID 38307625, 2024). "So far, only one study has monitored circulating levels of CXCL12 during ASFV infections." (PMID 36680273, 2023). "Additionally, pro-inflammatory cytokines, including MIF, PAI-1, IL-18, CXCL1, CXCL12 and IL-8, were statistically decreased (P < 0.05) in 10−6 M 1α,25(OH)2D3-pretreated A549 cells by 12 h post-infection." (PMID 36758060, 2023). "Current evidence from experimental infections suggests that CXCL12 favors WNV neuropathogenesis." (PMID 36992514, 2023). "Thus, the CXCL12/CXCR4 axis presents an excellent target for preventing infection and inflammation‐related PTL." (PMID 35318804, 2022). "Additionally, we reported that AMD3100 or CXCL12 (the CXCR4 natural ligand) fully inhibited infection of primary CD4+ T cells by cell-free X4-1 Env-pseudotyped viruses (, and here)." (PMID 35622876, 2022). "Thus, the CXCL12/CXCR4 axis presents a promising target for preventing infection and inflammation‐related PTL." (PMID 35318804, 2022). "Here, the infection decreased the expression of CXCL12 in bone marrow but increased its expression in the lung, liver, and spleen, suggesting that the different CXCL12 levels between tissues might drive the migration of CXCR4high MKs." (PMID 36524131, 2022). "As the CXCL12/CXCR4 chemotactic axis is important in many parts of the immune system, it may contribute to the greater susceptibility to infection observed in HHT." (PMID 34906163, 2021). "To test our hypothesis, we investigated whether the sensitivity of viruses to inhibition by CXCL12 changes during the course of infection." (PMID 33872329, 2021). "However, it inhibited less potently the late viruses, suggesting that X4 viruses evolve resistance to CXCL12 in the course of infection." (PMID 33872329, 2021). "In the following, we studied the mechanisms of resistance to CXCL12 and how it may be related to increased pathogenesis of the infection." (PMID 33872329, 2021). "Through analysis of thirty envelope glycoproteins (Envs) from patients at different stages of infection, mostly treatment-naïve, we first interrogated whether sensitivity of viruses to inhibition by CXCL12 varies over time in infection." (PMID 33872329, 2021). "However, we show that the expression in the thymus of Ccl25 and Cxcl12 is increased after infection with M. avium strain 25291." (PMID 34987496, 2021). "An alternative explanation could be a chronic elevation of the CXCL12 plasma level, described in severe infection and recently in HHT." (PMID 34906163, 2021).
infection (continued). "Although reduced compared to uninfected T84 cells, CXCL12/SDF-1 is still induced during 97-3250 infection and may allow for normal immune surveillance, while its absence during 4865/96 and HS infections may limit surveillance functions." (PMID 33194815, 2020). "Over the first 3 days of the infection, the concentration of CXCL12 in the bone marrow compartment halved, whereas the concentration in the peripheral blood and lungs increased 4-fold, consistent with a gradient of CXCL12 between the bone marrow and the lungs." (PMID 32460694, 2020). "Only infection with L2 stimulated production of GM-CSF, IL-1β, IL-6, IL-32, and CXCL12." (PMID 32039039, 2019). "Additionally, it was recently revealed that neutrophils can release the T cell chemokine CXCL12 while migrating to the site of infection." (PMID 31776393, 2019). "In this way, CXCL12 might inhibit CXCR4-tropic infection of memory CD4+ T cells and further inhibit the establishment of HIV latency." (PMID 29085362, 2017). "Future studies are necessary to examine the impact of US27 on CXCR4 during infection in various cell types to determine whether US27 actually promotes increased migration of infected cells towards CXCL12." (PMID 28207860, 2017). "Also, both groups obtained simultaneously evidence that CXCL12/SDF-1 prevented selectively the infection by T-tropic HIV isolates (laboratory adapted or primary) but was unable to prevent infection of activated T lymphocytes by M-tropic viral isolates." (PMID 26097474, 2015). "CXCL12 was produced mainly by pleural mesothelial cells during infection." (PMID 22511975, 2012). "Thus, modification of the CXCL12/CXCR4 axis grants control over the pathology's development in these infection models." (PMID 22511975, 2012). "Infection with all three viral strains induced a stark alteration in the distribution of CXCL12." (PMID 23116176, 2012). "Fourth, modulation of chemokines present in the nervous system, such as CXCL12, could play a role in the initial infection of the ganglia, sites of HSV latency, and increase the ability of HSV to persist and cause disease." (PMID 22319442, 2012). "Furthermore, the levels of the chemokines MCP1 and CXCL12 in BAL samples of infected mice during the chronic phase of infection were detected in IFN-γ R−/− mice during the chronic phase of infection." (PMID 22205929, 2011). "Therefore, we assume that CXCL12 may be involved in both pathologies by mediating processes such as post-infection T-cell activation in tonsils and mucosa, systemic migration of effector T cells, and secretion of B-cell-deficient IgA." (PMID 36793719, 2023). "It is possible that that infection could therefore lead to defective trophoblast invasion due to lack of essential attractant signalling molecules secreted from maternal decidua, such as CXCL12 and CXCL16." (PMID 28515460, 2017). "In addition, the CXCL12, APRIL and BAFF cytokines, which are associated with plasma cell homing and survival, were more highly expressed in the splenic tissue of animals with active infection and white pulp disruption." (PMID 27243459, 2016). "Indeed, the faster clearance of filarial infection appears in C57BL/6 mice, within which a strong increase of chemokine concentrations, including CXCL12, is measured in the pleural cavity, peaking at the time of the 4th molt, i.e. around one month post infection." (PMID 22511975, 2012). "Similar to our results, previous transcriptomic research in chickens has also shown increases in expression of TLR1B, CXCL12 and ACOD1 after infection with MG." (PMID 38370402, 2024). "Upon infection, increased levels of GCSF decrease the level of CXCL12 protein and therefore disrupt CXCL12-CXCR4 interaction and stimulate the release of neutrophils from the bone marrow into the blood." (PMID 38515741, 2024). "Results show that Envs resistant (RES) to CXCL12 are frequent in patients experiencing low CD4TL levels, most often late in infection, only rarely at the time of primary infection." (PMID 33872329, 2021).
infection (continued). "Results indicate that CXCL12 resistant (RES) viruses are common in patients with a severe drop in peripheral blood CD4TL levels, most often late in infection, in one case at the time of PHI." (PMID 33872329, 2021). "The analysis in this study revealed an increased inflammatory response, and the expression of CXCL1, CXCL12, CCL2 and CCL5 was significantly increased upon natural street RABV strain infection of dogs or humans compared to artificial mouse infection." (PMID 33081802, 2020). "As mentioned, we found that the expression of CXCL1, CXCL12, CCL2, CCL5 and TIMP-1 was significantly increased upon CGS-17 and CXZ-15 infection." (PMID 33081802, 2020). "We observed a significant decrease in TEER following infection with E-30 at a MOI of 0.7 after 24 h and 28 h, whereas the TEER in the uninfected conditions (UI and UI + CXCL12) remained stable throughout the experiment." (PMID 31752904, 2019). "We observed that E-30 infection enhances the migration of CD3+, CD4+, and CD8+ naive T cells across the BCSFB, especially once CXCL12 is apically present." (PMID 31752904, 2019). "We observed a slight, but significant increase in the paracellular flux following infection with E-30 at a MOI of 0.7, whereas the paracellular flux in the uninfected conditions (UI, UI + CXCL12) remained stable throughout the migration experiment." (PMID 31752904, 2019). "Aside from the role of CXCR7 in CXCL12-guided cell migration across the blood brain barrier (BBB), the higher CXCR7 cell surface expression on the HIV-susceptible CD14+ CD16+ monocytes might increase the likelihood of CXCR7 coreceptor use in subsequent infection cycles of CD14+ CD16+ monocytes." (PMID 29560468, 2018). "Importance of these chemokines in the mobilization of Treg cells to the lungs was demonstrated by the administration of anti-CXCL12 and anti-CCL5 neutralizing antibodies to mice prior infection and treatment with MDP." (PMID 29445379, 2018). "However, it is also possible that during infection, other viral genes may modify or ablate the effects of US27 on CXCR4 signaling, particularly UL33 and UL78, which have been found to associate with CXCR4 and impair CXCL12-induced signaling outcomes." (PMID 28207860, 2017). "One of the best recognized pathological function of CXCR4 is its role as a co-receptor during infection with human immunodeficiency virus (HIV)-1 and the ability of CXCL12 to interfere in the infection process, at least in vitro." (PMID 27664068, 2016). "At late phase of infection, high expression of both CCL19 and CXCL12 was observed only in control mice and correlated with the maintenance and the lymphoid organization of immune infiltrates composed of CD4+ and CD8+ T cells, macrophages, DC and FDC." (PMID 23717393, 2013). "In these experiments we transduced pLEC with increasing doses of CXCR7 adenovirus, harvested cells at 20 hours post-infection and performed quantitative RT-PCR analysis for mRNA expression of CXCR7, SDF-1/CXCL12 and ITAC/CXCL11." (PMID 23894550, 2013). "Mobilization of both immature and mature cells was accompanied by the reduction of BM SDF-1 (CXCL-12) levels and the reciprocal elevation of SDF-1 in the blood 24 h post infection." (PMID 23189271, 2012). "Several studies have shown that the CXCL12/CXCR4 axis is involved in the progression of diseases and infections." (PMID 22511975, 2012). "Expression of the chemokine receptor CXCR4, which shares the ligand CXCL12/SDF-1 with CXCR7, has been shown to be down-regulated in primary B cells upon infection by EBV." (PMID 21857817, 2011). "In contrast, analysis revealed that the levels of two factors, SDF-1α/CXCL12 and CD30L/CD153 were higher after infection with M3.MR in both the array and ELISA assays." (PMID 21445235, 2011). "Since the replication of X4LAI.04 virus induces a large release of CXCL12, the effect of ODN M362 on CXCL12 release is masked later in the infection, when significant viral replication occurs." (PMID 20862220, 2010).
infection (continued). "Within the first 60 h post-infection, X4LAI.04 virus induced a significantly higher release of CXCL12 from ODN M362-pretreated compared with a ligand-untreated tissue." (PMID 20862220, 2010). "As the X4LAI.04 infection of the ODN M362-treated tissues progressed, secretion of CCL4 and CXCL12 decreased and on day 9 p.i. became 30% lower (p = 0.047) than that produced by matched X4LAI.04-infected ligand-untreated tissues." (PMID 20862220, 2010). "VitD’s potential upregulation of CXCR4 could result from increased expression of its ligand, stromal cell-derived factor 1 (SDF1 or CXCL12), also predicted by the model, which has been observed to impede HIV entry, protecting against infection." (PMID 40149968, 2025). "Strikingly, upregulation of CXCL12 expression by endothelial cells is observed specifically in murine infection with SARS-CoV-2, but not after influenza A virus or MERS-CoV infection." (PMID 39773555, 2025). "CXCL12 mRNA in bone marrow homogenates increased after SARS2-N501YMA30 infection, while protein levels of CXCL12 failed to increase." (PMID 39773555, 2025). "Measurement of chemokines in the lung showed several alterations in global IFNLR1-/- mice compared to WT mice both during super-infection and single S. aureus infection, including increased TNFα, CXCL11, CXCL12, and MIP3α and decreased IL-1β, MIP1β, and CXCL16." (PMID 39178311, 2024). "In response to MG, gene expression is up-regulated at the infection site in pathogen-recognition receptors (e.g. TLR1B), signalling molecules and their receptors (such as CXCL12 and IL17R), adaptive cell-surface receptors (CD74) and various other immunomodulators (e.g. ACOD1)." (PMID 38370402, 2024). "However, at 30 days post-infection, TNF-α, IL-6, KC, CCL3, CCL2, CCL20, CXCL11, CCL11), CCL27, CXCL5, CXCL12 and CCL5 were all significantly higher in the BAL fluid of Duox1 KO compared to WT mice." (PMID 36936954, 2023). "If the infection persists, mature PNNs will no longer be sufficient and the SDF-1/CXCL12 pathway activation then participates in the recruitment of immature PNNs." (PMID 36012544, 2022). "Increased expression of CXCL12 in the cardiac tissue after XBJ and C0127s treatments may indicate a balanced neutrophil mobilization or improved clearance of infection." (PMID 33986658, 2020). "Considering that CXCL12 is the ligand that interacts with CXCR4 and CXCR7, these findings suggested that during a HP infection, CXCL12 regulates the homing B cell lymphocytes to gastric mucosa, and further promotes the abnormal growth of B lymphocytes through CXCL12/CXCR4 or CXCL12/CXCR7 signaling." (PMID 30999581, 2019). "Now, we compared the migration capacity of different subpopulations of naive T cells, (CD3+, CD4+, and CD8+ T cells) in presence or absence of the chemokine CXCL12 and/or E-30 infection." (PMID 31752904, 2019). "During infection, potentiation of CXCR4 signaling by US27 might promote increased migration of infected cells towards CXCL12-expressing tissues, such as the bone marrow." (PMID 28207860, 2017). "After 2 h of migration without chemokine as well as toward CCL19 or CXCL12, cells in the lower well were counted and infection efficiency was determined before and after migration." (PMID 28484459, 2017). "WT PR8 infection induced higher levels of proinflammatory cytokines, such as TNF-α, CXCL12, and interleukin 6 (IL-6), than infection with the segment 8 reassortant viruses, while the profiles in O175A- and O265B-infected mice were more similar to each other than to the profile in PR8-infected mice." (PMID 27489273, 2016). "Similarly, chemokine CXC ligand 12 (CXCL12) and chemokine (CXC motif) receptor 6 (CXCR6) were upregulated by infection in CHB." (PMID 27197554, 2016). "However, as we demonstrated, CC chemokines CCL3/MIP-1α, CCL4/MIP-1β, and CCL5/RANTES were unable to block infection by T-tropic isolates thus proving the specific and selective inhibition by CXCL12/SDF-1 for this type of viruses." (PMID 26097474, 2015).